FGF4 (fibroblast growth factor 4)
Diseases named in the same sentence as FGF4 in open-access papers (continued):
Sharing a sentence is not in itself a finding about the gene and the disease.
bladder cancer (4 papers, 2008 to 2023). "Here we first investigated the association between FGF4 and poor prognosis in bladder cancer, and we have also determined the “high-risk” nsSNPs towards the pathogenesis of bladder cancer by employing an in-silico approach." (PMID 35888106, 2022). "The prognostic value of FGF4 in bladder cancer remains to be elucidated, and the exact mechanism is yet to be deliberated." (PMID 35888106, 2022). "This has created an intrigue to investigate the role of FGF4 in bladder cancer and further elucidate its role in prognosis." (PMID 35888106, 2022). "In conclusion, a bioinformatics pipeline was developed to efficiently predict the deleterious effect of nsSNPs of FGF4 on bladder cancer." (PMID 35888106, 2022). "FGF4 gene showed a hazard ratio (HR) = 8.21 (95% CI, 1.13–9.58) and logrank p-value = 0.012 for bladder carcinoma indicating that the result was statistically significant (the relation between the high expression of the HLA-G gene and more survival rate)." (PMID 35888106, 2022). "Some large-scale experiments have suggested that aberrant amplification of FGF4 occurs in several types of cancer, including lymph node metastasis and urinary bladder cancer." (PMID 28384236, 2017). "FGF pathway genes, including FGF3, FGF4 and FGF8, are common targets of MMTV integration and FGFR3 mutations have been reported in 41% of bladder cancers." (PMID 18840272, 2008). "The role of FGF1 and FGF3 is evident in bladder cancer; however, the role of FGF4 is vague." (PMID 35888106, 2022). "However, to the best of our knowledge, the role of FGF4 in bladder cancer is limited, despite its prominent role in MAPK pathway activation linked with FGF1 and FGF3." (PMID 35888106, 2022). "The results indicated that the FGF4 gene deregulation might affect the overall survival rate of patients with bladder cancer and thus affecting prognosis significance." (PMID 35888106, 2022). "Furthermore, Kaplan Meier bioinformatics analyses indicated that the FGF4 gene deregulation affected the overall survival rate of patients with bladder cancer, leading to prognostic significance." (PMID 35888106, 2022). "Thus, based on these analyses, our study suggests that the reported nsSNPs of FGF4 may serve as potential targets for diagnoses and therapeutic interventions focusing on bladder cancer." (PMID 35888106, 2022).
lung carcinoma (4 papers, 2020 to 2025). "CLEC4M, SLC10A2 and FGF4 have been found to be involved in lung cancer progression and the regulation of treatment resistance." (PMID 33005178, 2020). "FGF4 is one of the representative paracrine FGFs binding to heparan-sulfate proteoglycan and fibroblast growth factor receptors, which are frequently amplified and overexpressed in lung cancer." (PMID 40849639, 2025). "Fibroblast growth factor (FGF) isoforms, such as FGF4, FGF19 and FGF7, promoted epithelial-mesenchymal transition (EMT), cell proliferation and migration during cancer progression by inducing store-operated calcium entry in lung carcinoma." (PMID 33005178, 2020).
breast tumors (3 papers, 2012 to 2021). "RARE MR images (TR = 5 s; TE = 14 ms) of immunocompetent mice bearing Ef43.fgf4 syngeneic breast tumors showed the tumors as hyperintense regions with respect to the psoas muscle." (PMID 34359704, 2021). "The presence of large numbers of F4/80+CD11b+ TAMs within the EF43.fgf4 breast-tumors was confirmed by optical microscopy methods." (PMID 34359704, 2021). "HR+ breast tumors regardless of HER2 status (HR+/HER2+ and HR+/HER2−) were more likely to harbor CNAs in CCND1, FGF3, FGF4, and FGF19, which colocalizes in chromosome 11q13.3." (PMID 32695676, 2020).
craniosynostosis (3 papers, 2022 to 2024). Craniosynostosis is defined as the premature fusion of one or more cranial sutures leading to secondary distortion of skull shape resulting in skull deformities with a variable presentation. "In humans, duplication of the chromosomal 11q13 region, which includes FGF3 and FGF4 causes intellectual disability, craniosynostosis and microcephaly." (PMID 39372737, 2024). "For instance, a constitutionally increased expression of the FGF4 gene is a risk factor for craniosynostosis." (PMID 35980984, 2022). "Also in humans, constitutional increases in FGF3 and FGF4 have been associated with an increased risk of craniosynostosis, and FGF4 has been shown to be a negative prognostic indicator for a number of cancers due to its effect on tumor growth, angiogenesis, invasion and metastasis." (PMID 38397188, 2024).
diabetes (3 papers, 2010 to 2026). "Compared with the diabetic group, the body weight of mice in the FGF4 treatment group increased slightly, suggesting that FGF4 can alleviate diabetes-induced weight loss." (PMID 41347806, 2026). "Given that oxidative stress is involved in the pathogenesis of diabetes-related lung injury, the present study first analyzed the effect of FGF4 on oxidative stress." (PMID 41347806, 2026). "After successful modeling, FGF4 intervention was administered to further investigate the role and potential mechanism of FGF4 in diabetes-related lung injury." (PMID 41347806, 2026). "Therefore, FGF4 may be a promising drug for treating lung damage caused by diabetes." (PMID 41347806, 2026). "It has been reported that FGF4 can alleviate diabetes and hyperglycemia." (PMID 41347806, 2026). "In this sense, combined therapy approach with VEGF-A and FGF4 genes may significantly improve the delayed wound repair in diabetes over the effect exerted by single VEGF-A treatment." (PMID 20804557, 2010). "Genetic knockout of AMPK or FOXO1 abrogated the protective effects of rFGF4 against diabetes-induced renal injury, underscoring the critical role of the AMPK-FOXO1 axis in mediating the therapeutic effects of FGF4 in DKD." (PMID 41290710, 2025). "In summary, FGF4 exhibits a significant mitigating effect on high-glucose-induced lung cell damage through the AMPK-PGC-1 signaling axis, providing a new strategy for the treatment of diabetes and its pulmonary complications." (PMID 41347806, 2026). "To further elucidate the role played by AMPK-FOXO1 in mediating the therapeutic effects of FGF4 on DKD, we established a mouse model with podocyte-specific knockout of Ampka1/a2 (Ampk-PKO) and subjected these mice to STZ-induced diabetes, followed by treatment with rFGF4 or vehicle control." (PMID 41290710, 2025). "Patients with diabetes often develop pulmonary complications and FGF4, as a novel long-acting glucose-regulating factor, can not only effectively regulate blood glucose but also alleviate pulmonary inflammation and injury through its anti-inflammatory and antioxidant properties." (PMID 41347806, 2026). "In summary, our study demonstrates that podocyte-derived FGF4 activates the FGFR1-AMPK-FOXO1 signaling pathway to mitigate oxidative stress and promote podocyte survival, thereby preserving glomerular integrity and protecting the kidney from diabetes-induced injury." (PMID 41290710, 2025). "Therefore, FGF4 delivered alone, although possessing the ability to up-regulate the endogenous VEGF-A expression, may be ineffective in reparative processes in diabetes." (PMID 20804557, 2010).
gastric cancer (3 papers, 2008 to 2024). A primary or metastatic malignant neoplasm involving the stomach. "The FGF4 gene, which was initially identified as an oncogene in gastric carcinoma, can induce neoplastic transformation of NIH-3T3 cells, as well as epithelial–mesenchymal transition (EMT) by modulating calcium ion channels in lung adenocarcinoma." (PMID 39590120, 2024). "Another study showed that the downregulation of miR-491-5p also promotes the metastasis of gastric cancer via SNAIL and FGF4." (PMID 34590612, 2021). "DNA amplification was detected at chromosomal regions 17q21.1(harboring HER-2), 11q13.3 (CCND1), and 11q13 (FGF4) in four, three, and three tumors, respectively, though the amplification was not correlated with any clinicopathological feature of the gastric cancers." (PMID 19115996, 2008).
hepatocellular carcinoma (3 papers, 2009 to 2023). A malignant tumor that arises from hepatocytes. "Critical genes encoded by this region include CCND1, FGF3, FGF4, which are involved in cell-cycle regulation and tumor cell proliferation in oral squamous cell carcinoma, hepatocellular carcinoma, and ESCC11,54–56." (PMID 34285259, 2021). "For example, inhibition of FGF19 in CCND1-amplified tumors (11q13 amplification) using anti-FGF19 antibodies has been shown to be an effective therapy for hepatocellular carcinoma (HCC), and the blockage of its FGFR receptors has shown promising clinical results in FGF19/FGF4+ HCC." (PMID 36980521, 2023).
liver cancer (3 papers, 2019 to 2023). An epithelial or non-epithelial malignant neoplasm that arises from the liver. "In patients with liver cancer, FGFs (FGF2, FGF4, FGF5, FGF9, and FGF22) are overexpressed." (PMID 31031647, 2019).
liver fibrosis (3 papers, 2014 to 2022). "The present study was undertaken to examine the possible effects of HGF and FGF4 pretreated MSCs on CCl4 injured hepatocytes and liver fibrosis." (PMID 25685159, 2015). "We established MSCs culture and treated with HGF and FGF4 to increase their repair potential in liver fibrosis." (PMID 25685159, 2015). "Moreover, the transplantation of HGF and FGF4 pretreated MSCs contributed to the improvement of liver function and in reduction of fibrosis in CCl4-induced mice liver fibrosis." (PMID 25685159, 2015). "Interestingly, all these growth factors have been linked to fibrosis: PDGF-B in liver fibrosis, EGF in heart and renal fibrosis and FGF-4 in lung and renal fibrosis." (PMID 25280005, 2014).
lung adenocarcinoma (3 papers, 2016 to 2024). A carcinoma that arises from the lung and is characterized by the presence of malignant glandular epithelial cells. "However, the frequency and potential role of FGF4 amplification in the pathogenesis of lung adenocarcinoma require further investigation." (PMID 39590120, 2024). "Using two lung adenocarcinoma (ADC) cell lines, A549 and H1299, we showed that FGF4, but not FGF7, altered cell morphology, promoted EMT-associated protein expression, and enhanced cell proliferation, migration/invasion and colony initiation." (PMID 27677589, 2016).
achondroplasia (2 papers, 2020 to 2024). Achondroplasia is the most common form of chondrodysplasia, characterized by rhizomelia, exaggerated lumbar lordosis, brachydactyly, and macrocephaly with frontal bossing and midface hypoplasia. "Specific human disease conditions such as achondroplasia, where underlying genetic causes (FGFR3 gain-of-function mutations) are defined, may have specific molecular mechanistic similarities to FGF4 overexpression and IVDD (potentially signaling through FGFR3) in dogs." (PMID 32793650, 2020).
acute myocardial infarction (2 papers, 2021 to 2025). Necrosis of the myocardium, as a result of interruption of the blood supply to the area. "FGF4+AA-treated BG01 hESC-CMs robustly released acute myocardial infarction (AMI) biomarkers (cTnI, CK-MB, and myoglobin) into culture medium in response to hypoxic injury." (PMID 34685725, 2021). "In particular FGF1, FGF2, and the herein not analysed FGF4 show promising results in clinical trials to improve angiogenesis after myocardial infarction or angina pectoris." (PMID 39940657, 2025).
angina (2 papers, 2021 to 2025). "The transfer of human FGF4 bound to an adenovirus (Ad5-FGF4) vector by intracoronary infusion resulted in increased FGF mRNA production at twelve weeks, enhanced collateral dependent perfusion, and lessened the severity of symptomatic angina in patients in the AGENT trial." (PMID 33918396, 2021).
Brachycephaly (2 papers, 2021 to 2022). An abnormality of skull shape characterized by a decreased anterior-posterior diameter. "The results of these studies show association of brachycephaly with the RUNX2 gene on CFA12, SMOC2 on CFA1 and BMP3 on CFA32, chondrodysplasia with FGF4 retrogene on CFA12 and CFA18 and also with skull size." (PMID 36230363, 2022).
coronary artery diseases (2 papers, 2013 to 2021). "Hypoxia-responsive genes and potential cardiac biomarkers proved in the diagnosis and prognosis of coronary artery diseases were induced in FGF4+AA-treated BG01 hESC-CMs in response to hypoxia based on transcriptome analyses." (PMID 34685725, 2021).
embryonal carcinoma (2 papers, 2011 to 2013). A non-seminomatous malignant germ cell tumor characterized by the presence of large germ cells with abundant cytoplasm resembling epithelial cells, geographic necrosis, high mitotic activity, and pseudoglandular and pseudopapillary structures formation. "Both fgf4 and utf1 are typical Sox2 target genes, therefore, we used two biotin-labeled DNA probes, covering the Sox2-binding sites in fgf4 and utf1 respectively, to enrich endogenous Sox2 from P19 embryonal carcinoma cells." (PMID 22046437, 2011).
esophageal adenocarcinoma (2 papers, 2019 to 2020). A malignant tumor with glandular differentiation arising predominantly from Barrett mucosa in the lower third of the esophagus. "Use case – Esophageal adenocarcinoma with reported amplification ofCCND1,MAP2K1,RICTOR,FGF10,FGF19,FGF3,FGF4 andMCL1." (PMID 31608148, 2019).
Hepatic steatosis (2 papers, 2024 to 2025). Steatosis is a term used to denote lipid accumulation within hepatocytes. "FGF4 exerts antihyperglycemic effects, protects against hepatic steatosis in metabolic-associated fatty liver disease and mediates bile acid homeostasis under cholestatic stress." (PMID 40585885, 2025). "On a positive note, loss of Fgf4 in mice increased hepatic steatosis and liver damage, suggesting FGF4 is important to maintain hepatic health." (PMID 39766329, 2024).
Hepatitis (2 papers, 2024 to 2025). Inflammation of the liver. "Therefore, we investigated whether FGF4 can regulate M1 macrophage and thereby help treat liver inflammation in AIH." (PMID 39095789, 2024).
Hyperglycemia (2 papers, 2022 to 2026). An increased concentration of glucose in the blood. "It is important to mention that most other FGF family members (such as FGF21 and FGF23) have been widely reported for their association with hyperglycemia, whereas research on FGF4 remains relatively limited." (PMID 41347806, 2026). "Remarkably, we also found a significant positive correlation between FGF4 and blood hyperglycemia, suggesting that it can be a potent and potentially indicator for GDM." (PMID 35317005, 2022).
intervertebral disc degeneration (2 papers, 2025). "The predisposition is particularly linked to the expression of a fibroblast growth factor 4 (FGF4) retrogene on chromosome 12, which is associated with dramatically accelerated intervertebral disc degeneration." (PMID 40281988, 2025). "A prime example is the occurrence of premature intervertebral disc degeneration in chondrodystrophic dog breeds, which is linked, for example, with a high allele frequency of the CFA12 FGF4 retrogene." (PMID 40266989, 2025).
lymph node metastasis (2 papers, 2017 to 2018). "As mentioned, FGF4 is an important gene for driving lymph node metastasis." (PMID 30540749, 2018).
non-alcoholic fatty liver disease (2 papers, 2024 to 2025). "In a study of non-alcoholic fatty liver disease, FGF4 supplementation reduced liver inflammation by inhibiting hepatocyte apoptosis and adipose macrophage infiltration." (PMID 39095789, 2024).
osteoporosis (2 papers, 2022 to 2023). A condition of reduced bone mass, with decreased cortical thickness and a decrease in the number and size of the trabeculae of cancellous bone (but normal chemical composition), resulting in increased fracture incidence. "Similarly, the FGF2, FGF4, FGF10, FGF18, and FGF22 genes, which showed interactions with the FGFRL1 gene, were associated with height, hypertension, and osteoporosis." (PMID 35980984, 2022). "The FGF10, FGF18, FGF2, FGF4, and FGF22 genes, which interact with FGFRL1, were correlated with height, hypertension, and osteoporosis." (PMID 35980984, 2022).
Ataxia (1 paper, 2022). Ataxia refers to impaired coordination of voluntary muscle movement. "The pathway related to growth factors (FGF4, FGF22, and PDGFD), RTK, and PLCB4 was also associated with visual processing defects, ataxia, absence seizures, epilepsy, and Huntington's disease." (PMID 36457060, 2022).
chondrosarcoma (1 paper, 2024). A malignant cartilaginous matrix-producing mesenchymal neoplasm arising from the bone and soft tissue. "To investigate whether FGF4, FGF8, and FGF9 induce differential signaling via FGFR1c (referred to as FGFR1 here), we used rat chondrosarcoma (RCS) chondrocytes, an immortal chondrocyte cell line used to model proliferating chondrocytes in the developing limb." (PMID 38568193, 2024).
Cognitive impairment (1 paper, 2023). Abnormal cognition is characterized by deficits in thinking, reasoning, or remembering. "In terms of other neurological conditions, FGF4 expression was upregulated in patients’ CSF transitioning from mild cognitive impairment to AD progression." (PMID 36650549, 2023).
diabetic foot ulcers (1 paper, 2021). "FGF1, FGF2, FGF4, FGF7, FGF16, FGF21, and FGF23 have been found to have good therapeutic outcomes for diabetic foot ulcers." (PMID 34831463, 2021).
diabetic kidney disease (1 paper, 2025). Progressive kidney disorder caused by vascular damage to the glomerular capillaries, in patients with diabetes mellitus. "Here the authors use genetic models to show that podocyte FGF4 is protective of diabetic kidney disease progression, and that treatment with recombinant FGF4 reduced renal injury and fibrosis in diabetic mouse models." (PMID 41290710, 2025).
dilation (1 paper, 2022). "Obviously, further investigation is necessary to elucidate the cellular and molecular mechanisms by which the Notch/FGF4 signaling axis regulates the RT development and the association of the pathogenesis of cystic dilation of the RT." (PMID 34101112, 2022).
Encephalocele (1 paper, 2024). A neural tube defect characterized by sac-like protrusions of the brain and the membranes that cover it through openings in the skull. "In line with the rescue of the encephalocele phenotype, Fgf3 and Fgf4 levels were significantly reduced in the midbrain of ABEs-C4Δ mutants as compared to wildtype littermates or C1-C4Δ mutants." (PMID 39372737, 2024).
germ cell cancers (1 paper, 2011). "Undifferentiated NT2 cells also express the protein FGF-4, which is abundant in a subset of germ cell cancers and promotes malignant growth of cultured ECs." (PMID 21799949, 2011).
germ cell tumor (1 paper, 2013). A benign or malignant, gonadal or extragonadal neoplasm that originates from germ cells. "Early studies suggested that FGF-4 was overexpressed in different germ cell tumors." (PMID 24159602, 2013). "Another immunohistochemical study on primary testicular germ cell tumors showed predominant expression of FGF-4, FGF-8, and FGFR1 in non-seminomatous and highly proliferative components of the tumors." (PMID 24159602, 2013).
gestational diabetes (1 paper, 2022). Carbohydrate intolerance first diagnosed during pregnancy. "Our study showed that human recombinant FGF4 (rFGF4) improved maternal glucose tolerance in high fat diet (HFD) induced gestational diabetes mice, and decreased neural tube defects (NTDs) of embryos in both HFD induced and streptozotocin (STZ) induced gestational diabetes mice." (PMID 35317005, 2022).
glioma (1 paper, 2018). A benign or malignant brain and spinal cord tumor that arises from glial cells (astrocytes, oligodendrocytes, ependymal cells). "Fibroblast growth factor 4 (FGF4) also has been correlated with a greater malignancy profile in high-grade gliomas.The radioresistant cells had upregulated expression of many anti-apoptotic genes, including BCL2, CD74, and WT1, which regulates GBM cells proliferation and apoptosis." (PMID 30344926, 2018).